EPHB2 (EPH receptor B2)
Diseases named in the same sentence as EPHB2 in open-access papers (continued):
Sharing a sentence is not in itself a finding about the gene and the disease.
colorectal cancer (continued). "We previously tested the expression of EphB2 in more than 100 cell lines using flow cytometry and found that breast cancer MDA-MB-231, lung mesothelioma NCI-H226, and colorectal cancer LS174T showed the EphB2 expression." (PMID 40943224, 2025). "The downregulation of EPHB2, involved in cell cycle processes, and LEFTY1, involved in intestinal mucosal immunity and TGF-β signaling, is a common feature also observed in colorectal cancers and Crohn’s disease, respectively." (PMID 39285481, 2024). "However, EphB2 may play a diverse role in colorectal cancer." (PMID 32226496, 2020). "To evaluate the effects of EphB2 depletion, we selected the SW620 colorectal carcinoma cell line, which contains abundant EphB2, whereas EphB1, EphB3, and EphB4 are undetectable and EphA4 is detected at low levels." (PMID 31545551, 2019). "Following co-immunofluorescence and image analysis, the number of EPHB2+ and ERBB3+ cells was quantitated in 15 colorectal cancers (3500 cells per tumour)." (PMID 26367378, 2015). "Multiple antibodies directed against LGR5 (Sigma-Aldrich, HPA012530; Abgent, AP2745; Abcam, ab75850), CD44 (Abcam, ab41478) and EPHB2 (R&D, AF467) were tested on normal human colon and colorectal cancer tissues." (PMID 26367378, 2015). "Recent advances in colorectal cancer have led to the characterisation of intestinal stem cell markers, including LGR5, EPHB2, and CD44." (PMID 26367378, 2015). "A qRT-PCR analysis of EPHB2 and ERBB3 expression levels was also conducted using 6 colorectal carcinoma cell lines." (PMID 26367378, 2015). "EPHB2- and LGR5-enriched cells reportedly comprise a stem-like cell population in human colorectal cancers." (PMID 24340024, 2013). "Since the EPHB receptors (EPHB2, EPHB3 and EPHB4) follow a similar pattern of transcriptional silencing in colorectal cancers, all EPHB receptor family members probably play a similar role in this disease." (PMID 18682749, 2008). "Therefore, 2H9 was further developed into an antibody-drug conjugate (ADC) to monomethylauristatin E and showed the antitumor efficacy to EphB2-overexpressed fibrosarcoma HT1080 and colorectal cancer xenografts." (PMID 40943224, 2025). "Unlike other gastrointestinal tumors, such as colorectal cancer, where EphB2 expression is lost during the adenoma-to-adenocarcinoma transformation, its activation persists in BE-EAC, promoting tumor progression." (PMID 40149421, 2025). "We analyzed the correlation between stemness markers and cholesterol biosynthesis genes in TCGA colorectal cancer (COADREAD) cohort and revealed positive correlations between CSC markers (EphB2 and CD44) and cholesterol biosynthesis genes (HMGCR, HMGCS1, FDPS, and FDFT1)." (PMID 34621019, 2021). "The HT‐29 colorectal carcinoma cell line, which needs EphrinB2 to survive, contains abundant EphB4 but not EphB1, EphB2, EphB3, or EphA4 proteins, as observed previously." (PMID 31545551, 2019). "EphB2 is important in cell motility, epithelial mesenchymal transition (EMT), adhesion and angiogenesis, and appears prognostic in multiple other malignancies, especially colorectal cancers." (PMID 27574806, 2016). "Also cell lysates from mouse brain and human colorectal cancer cells (HCT116, SW620) with reported EPHB2 expression, were used." (PMID 26870995, 2016). "We analysed whether EPHB2, a defined stem cell marker, co-localised with ERBB3 expression in colorectal cancer tissues." (PMID 26367378, 2015). "In colorectal cancer, EphA2 and EphB2, belonging to the tyrosine kinase receptor family, have been identified as novel markers for colorectal CSCs, whose expression is strongly correlated with the expression of CD44 and Lgr5, as well as the stemness of colorectal cancer cells." (PMID 41346572, 2025).
colorectal cancer (continued). "Based on the expression of EPHB2 stem cell marker and the ERBB3 differentiation marker, we tentatively propose that colorectal cancers are organised into i) stem-like cell enriched tumours, ii) differentiated tumours with a stem-like cell compartment or iii) lacking an EPHB2 stem cell compartment." (PMID 26367378, 2015). "To further investigate whether the Lgr5+ cells in human GAs had any stem cell properties, we analyzed the levels of ISC markers such as ASCL2, EPHB2, and OLFM4, which are highly expressed in stem-like cells from human colorectal cancers, as well as in murine intestinal adenomas." (PMID 24340024, 2013). "In conclusion, our data suggest that EPHB2 and ERBB3 identify different sub-types of colorectal cancer, including stem cell enriched tumours (EPHB2+/ERBB3-), tumours that contain mutually exclusive compartments (EPHB2+/ERBB3+) or tumours lacking an EPHB2 stem cell compartment (EPHB2-)." (PMID 26367378, 2015).
prostate carcinoma (27 papers, 2006 to 2025). A carcinoma that arises from epithelial cells of the prostate gland. "Among the 95 NLS genes, the expression of ARHGEF2, LHX2, and EPHB2 is close associated with clinicopathologic features and shortened disease-survival outcomes in prostate cancer patients." (PMID 36159187, 2022). "EphB2 expression was frequently found to be decreased in prostate cancer (PC) tissues with somatic mutational inactivation occurred in approximately 10% of sporadic tumors." (PMID 35223830, 2022). "Among the 95 NLS genes, the expression of ARHGEF2, LHX2, and EPHB2 is close associated with shortened disease survival in prostate cancer patients." (PMID 36159187, 2022). "Support for EphB2 functioning as a tumour suppressor in prostate cancer comes from the identification of its mutational inactivation; when DU-145 cells were transfected with a wild-type EphB2, clonogenic growth was suppressed." (PMID 33430066, 2021). "After performing single-cell RNA-seq on prostate cancer cell lines and circulating tumor cells from patients, we identified that upregulated gene expression in the EphB2 and Src pathways are associated with advanced malignancy." (PMID 31805710, 2019). "Loss of function mutations in the EphB2 gene have been shown to be associated with prostate cancer risk in African American men with positive family histories." (PMID 25148033, 2014). "For example, EphB2 kinase domain inactivating mutations have been found in prostate cancer cell lines, implicating a role for EphB2 as a tumour suppressor." (PMID 23627399, 2013). "The EphB2 gene encodes the EPHB2 receptor tyrosine kinase and was previously identified by our group as a tumor suppressor gene in prostate cancer." (PMID 21603658, 2011). "Here, we undertook a study to determine if genetic variation at the EphB2 locus is associated with risk of sporadic prostate cancer among African American men." (PMID 21603658, 2011). "To test for association between genetic variation at the EphB2 locus and risk of sporadic prostate cancer among AAM, we performed a detailed case/control candidate gene association study." (PMID 21603658, 2011). "The EPHB2 tyrosine kinase was first reported as a prostate cancer tumor suppressor gene, harboring somatic mutations in prostate tumors." (PMID 21603658, 2011). "We have previously shown an association between an EphB2 germline nonsense variant and risk of familial prostate cancer among African American Men (AAM)." (PMID 21603658, 2011). "An independent study looking at 72 probands from African American hereditary prostate cancer families identified 10 sequence variants in the EphB2 gene." (PMID 21603658, 2011). "Single marker-based logistical regression analyses revealed seven EphB2 SNPs showing statistically significant association with prostate cancer risk in our population." (PMID 21603658, 2011). "Somatic mutations in EPHB2 have been observed both in colorectal and prostate tumors, and an EPHB2 germline mutation has been associated with an increased prostate cancer (PC) risk." (PMID 16740153, 2006). "EphB2 also provides a tumor suppressor function in prostate cancer where loss of function mutation is accompanied by the increased risk for the development of prostate cancer." (PMID 25148033, 2014). "Additionally, a germline EphB2 nonsense variant (3055A>T; K1019X) was positively associated with risk of familial prostate cancer in African American men from high-risk families." (PMID 21603658, 2011). "Although a previous association study of the EphB2 gene has focused on coding region variants in familial prostate cancer cases, we have set out to determine if genetic variation at the EphB2 locus is associated with risk of sporadic prostate cancer in African Americans." (PMID 21603658, 2011).
prostate carcinoma (continued). "It has also been reported that EphB2 has a role in the maintenance of normal tissue architecture in the prostate and mutational inactivation is present in a significant fraction of prostate tumors, suggesting a role for EphB2 in the progression and metastasis of prostate cancer." (PMID 20624275, 2010). "A Pseudomonas aeruginosa electron transfer protein called azurin inhibits ephrin interaction to EphB2 and interferes with upstream signalling, which slowed down the proliferation of prostate cancer cells." (PMID 36830852, 2023). "EPHB2 acts as EPHB2, a suppressor of prostate cancer cells, is able to exert its tumor suppressive effect by inhibiting the activity of lipogenic factors DGAT1, DGAT2 and promoting the lipolytic factor ATGL, PEDF." (PMID 35912266, 2022). "Collectively, these results suggest the potential of ARHGEF2, LHX2, and EPHB2 as indicators of poor survival for advanced prostate cancer." (PMID 36159187, 2022). "For instance, EphA2 and EphB2 both promote tumor angiogenesis, but EphA2 is upregulated in prostate cancer, while EphB2 is downregulated." (PMID 33614496, 2020). "Soy phytoestrogens, genistein, and daidzein showed the protective effect of soy against prostate cancer by promoting demethylation of GSTP1 and EPHB2 promoter regions in prostate cancer cells." (PMID 31597327, 2019). "These taken together showed that EphB2 and Src pathways predict high-grade prostate tumors and poor prognosis in the TCGA prostate cancer patient cohort." (PMID 31805710, 2019). "In prohibition experiments with siRNAs of SRC and EPHB2, the cell motility and invasive capabilities of metastatic prostate cancer cells were attenuated (−15% in cell motility with siEPHB2 treatment, −49% in cell invasion with siSRC treatment)." (PMID 31805710, 2019). "The upregulation of parts of the EphB2 and Src pathways also predicts poor prognosis in the prostate cancer patient cohort of The Cancer Genome Atlas." (PMID 31805710, 2019). "Our previous studies of prostate cancer cell lines identified EPHB2 as a target for similar deletion-truncation events in the DU-145 cells." (PMID 19432969, 2009). "In the PC3 human prostate cancer cell line, EphA2 coimmunoprecipitated with EphB2 via the ligand binding domain, showing a co-clustering of these receptors that may differentially affect the Eph-ephrin signaling landscape based on the present heteromers." (PMID 38984128, 2024). "The role of ATGL in prostate cancer cells is also regulated by ephrin B2 receptor (EPHB2)." (PMID 35912266, 2022). "However, EphB2 expression and its specific functions in gastric cancer and prostate cancer are controversial and need to be further studied." (PMID 35223830, 2022). "Interference of EphB2 and Src signaling using dasatinib and specific siRNAs inhibits the disruption of cortical actin meshwork and attenuates invasion and migration in advanced prostate cancer cells." (PMID 31805710, 2019). "Although the exact function of EphB2 in normal urothelium is unknown, this reciprocal expression of EphB2 and EphB4 is reminiscent to what has been observed in colon and prostate cancer." (PMID 25148033, 2014). "EphB2 also plays an important role in familial prostate cancer." (PMID 25148033, 2014). "In addition, EphB2 has been identified as a tumor suppressor gene in prostate cancer." (PMID 24959213, 2014). "Although this approach led to identification of a previously unknown mutation in the receptor tyrosine kinase gene EPHB2 in the DU145 prostate cancer cell line, combining GINI and aCGH is not the best strategy for prostate cancer cells." (PMID 19737411, 2009).
prostate carcinoma (continued). "Specifically, it significantly decreased methylation at the promoter regions of BRCA1, GSTP1, and Eph receptor B2 (EPHB2) in DU-145 and PC-3 prostate cancer cell lines, leading to cell cycle arrest in the G0/G1 phase." (PMID 41226811, 2025). "Our results provide evidence that overexpression of the EphB2 and Src signaling pathways regulate EGFR dynamics and cellular aggressiveness in some advanced prostate cancer cells." (PMID 31805710, 2019). "We also examined the expression of other EphB receptor family members (EphB1, EphB2, EphB3) with no change in normal and prostate cancer." (PMID 40044981, 2025). "Here we have analyzed the EPHB2 gene for germline alterations in 101 individuals either with 1) CRC and a personal or family history of prostate cancer (PC), or 2) intestinal hyperplastic polyposis (HPP), a condition associated with malignant degeneration such as serrated adenoma and CRC." (PMID 16740153, 2006).
breast carcinoma (26 papers, 2009 to 2025). "Higher levels of EphB2 expression were associated with poor survival in breast cancer patients, suggesting it has prognostic value." (PMID 33430066, 2021). "EphB2 is involved in the development of breast cancer and increased EphB2 protein expression was negatively associated with overall patient survival." (PMID 28726720, 2017). "Cox regression was used in univariate and multivariate analyses to test if there was an independent association between EPHB2 protein expression and the presence of distant metastases, local metastasis or death due to breast cancer." (PMID 26870995, 2016). "In breast cancer, EphB2 expression has been associated with a longer relapse-free survival." (PMID 37958393, 2023). "The finding that high EphB2 levels associate with shorter DMFS suggests that EphB2 could be a predictor of metastatic progression, specifically in luminal types of breast cancer." (PMID 34360867, 2021). "A recent study indicates the association of EphB2 expression with breast cancer survival." (PMID 29682554, 2018). "Among Eph receptors, EphB2 is overexpressed in various tumors, including breast cancer, glioblastoma, mesothelioma, and hepatocellular carcinoma, which correlates with poor clinical prognosis." (PMID 40943224, 2025). "Only CSF1R and EPHB2 (BL2 subtype-specific TK genes) were reported as having similar expression in different types of breast cancer, including TNBC." (PMID 36672350, 2023). "EphB2 is overexpressed in most tumors, such as hepatocellular carcinoma, breast cancer, glioma, and malignant mesothelioma, and it functions as a tumor promoter." (PMID 35223830, 2022). "EphB2 was reported to be expressed in benign tissues, but it was significantly upregulated in breast cancer, especially in invasive and metastatic carcinomas." (PMID 35223830, 2022). "In many different human tumors, such as breast cancer, cervical cancer, and medulloblastoma, EphB2 acts as a tumor promoter that promotes migration and invasion of tumor cells, and its expression is upregulated." (PMID 35223830, 2022). "To that end, we assessed different clinical outcomes according to EphB2 expression in each subtype of breast cancer." (PMID 34360867, 2021). "Our earlier work demonstrated that EphB2 expression suppresses the growth of human breast cancer cells both in vitro and in vivo." (PMID 34360867, 2021). "Although our previous findings shed light on the role of EphB2 in breast cancer, they raise questions about the possibility of dual or even apparently contradictory functions." (PMID 34360867, 2021). "On the other hand, the varying impact of EPHB2 expression in breast cancer patients’ clinical outcomes reflects the complex role of EPH/ephrin molecular mechanisms in tumorigenesis." (PMID 34445116, 2021). "Here we analyzed the clinical significance of concomitant expression of EphB2 and its cognate ephrin ligands in the context of breast cancer progression." (PMID 34360867, 2021). "An example of a particular focus in our laboratory is investigating the roles of EphB2 and ephrin ligands in breast cancer." (PMID 34360867, 2021). "The impact of EphB2 gene expression on breast cancer is likely to be influenced by the co-expression of the genes that encode ephrin (EFN) ligands." (PMID 34360867, 2021). "Studies in human breast cancer have shown that the expression of EPHB2 can induce the increase of ATG5/12 and LC3II, thereby inducing autophagy." (PMID 33937013, 2021). "To assess the clinical pertinence of this concern, we performed a systematic review and meta-analysis of the prognostic/predictive value of EphB2 and its multiple cognate ephrin ligands in breast cancer." (PMID 34360867, 2021). "Ephrin-B1 was also shown to be important for EphB2-induced invasion in at least one breast cancer cell line." (PMID 34360867, 2021). "In breast cancer, EphB2 expression inhibits cell proliferation, motility and migration in vitro and has been described as a positive prognostic factor." (PMID 34943502, 2021).